RN7SKP92 (RN7SK pseudogene 92)
Gene: Miscellaneous RNA gene on chromosome 14 (100,487,544 to 100,487,787, forward strand). Ensembl gene ENSG00000253075.
Homologues: Orthologues: chimpanzee 7SK (99% identical). Paralogues in human: RN7SKP45 (64% identical), 7SK (64% identical), RN7SKP78 (63% identical), RN7SKP9 (63% identical), RN7SKP176 (63% identical), RN7SKP180 (63% identical), RN7SKP204 (63% identical), RN7SKP189 (62% identical), RN7SKP200 (62% identical), RN7SKP230 (62% identical), RN7SKP239 (62% identical), RN7SKP269 (62% identical), and 284 more.